NRP1 (neuropilin 1)
Diseases named in the same sentence as NRP1 in open-access papers (continued):
Sharing a sentence is not in itself a finding about the gene and the disease.
COVID-19 (continued). "Researchers have shown elevated NRP-1 RNA expression in SARS-CoV-2–positive cells, but not uninfected bystander cells, isolated from bronchioalveolar lavage of patients with severe COVID-19." (PMID 33395426, 2021). "NRP1 level is mildly decreased, but still quite abundant in peripheral blood of ICU admitted COVID-19 patients, while not changed in lung of COVID-19 patients compared with health control." (PMID 34168096, 2021). "NRP1 is decreased, but still quite abundant, in the peripheral blood of ICU COVID-19 patients, and not altered in lung of COVID-19 patients compared with controls." (PMID 34168096, 2021). "Results show that the expression of NRP1 is decreased in peripheral blood of COVID-19 patients who are admitted into intensive care unit (ICU), but not in non-ICU COVID-19 patients." (PMID 34168096, 2021). "The contribution of mdig-dependent expression of NRP1, NRP2 and genes in inflammation and glycosylation, to the pathogenesis of COVID-19 does not challenge the fact that ACE2 is the main receptor of SARS-CoV-2." (PMID 34335974, 2021). "Recent literature has established NRP1 as a coreceptor that facilitated SARS-CoV-2 cell entry and infectivity, and NRP1 mRNA expression was elevated in SARS-CoV-2-infected cells, but not in uninfected cells from severe COVID-19 patients." (PMID 34497683, 2021). "A paired Wilcoxon test comparing NRP1 and ACE2 expression within each sample showed a non-significant trend in controls (p = 0.0625), while a statistically significant difference was observed in COVID-19 patients (p = 0.03125), with NRP1 consistently exceeding ACE2 levels." (PMID 40722799, 2025).
glioma (118 papers, 2008 to 2025). A benign or malignant brain and spinal cord tumor that arises from glial cells (astrocytes, oligodendrocytes, ependymal cells). "Expression of NRP1 in tumor-associated macrophages/microglia was previously documented in gliomas and correlates with an immunosuppressive and tumor promoting pathway." (PMID 40805120, 2025). "NRP1 expression has been shown to be correlated with poor prognosis, glioma grade, and associated with the mesenchymal tumor subtype." (PMID 39201395, 2024). "Increased NRP1 expression is associated with shorter patient overall survival either when glioma types are analyzed together or when only GBM tumors are analyzed." (PMID 37894289, 2023). "Elevated Nrp1 expression in microglia and macrophages have been linked with a poor prognosis in gliomas." (PMID 36203599, 2022). "Neuropilin 1 (NRP1) expression is correlated with poor prognosis and glioma grade, and associates with the mesenchymal GBM subtype." (PMID 34071306, 2021). "Our group has reported the expression of Nrp1 by glioma associated microglia and macrophages (GAMs) associated with glioma biopsies of various grades." (PMID 32914058, 2018). "Here we build on our previous findings, which describe how the multi-functional co-receptor Neuropilin-1 (NRP1) signals through glioma associated microglia/macrophages (GAMS) to promote murine glioma, and investigate NRP1 expression in human glioma." (PMID 30479695, 2018). "We find that NRP1 expression is correlated with poor prognosis, glioma grade, and associates with the mesenchymal GB subtype." (PMID 30479695, 2018). "We describe here our analysis of two questions: 1) Is NRP1 expression correlated with glioma prognosis and 2) Can NRP1 expression be linked to pro-tumorigenic GAMs of the TME." (PMID 30479695, 2018). "Various studies have implicated most of the soluble factors known to signal via Nrp1 to be associated with poorer clinical outcomes and direct promotion of glioma growth in animal studies." (PMID 32914058, 2018). "We demonstrate, using an in vivo orthotopic glioma model, that tumors in mice with Nrp1-deficient GAMs exhibit less vascularity, grow at a slower pace, and are populated by increased numbers of anti-tumorigenic GAMs." (PMID 26755653, 2016). "Our results demonstrate that Nrp1 ablation from GAMs or pharmacologic inhibition of Nrp1 signaling causes anti-tumorigenic GAMs to infiltrate and accumulate at the actively expanding glioma border." (PMID 26755653, 2016). "Association between the levels of Sema3A/NRP1 and survival of patients with glioma." (PMID 37788099, 2023). "While Nrp1 receptor knockdowns were not assessed, there may be an association between Sema3C -mediated glioma stemness through Nrp1/PlexinA2/PlexinD receptor binding and downstream Rac1 activation." (PMID 36203599, 2022). "have shown that NRP1 is expressed by macrophages and microglia associated with gliomas." (PMID 34277411, 2021). "NRP1 expression on glioma-associated macrophages (GAM) induces a pro-tumoral response." (PMID 32766254, 2020). "It should be noted that high NRP1 expression was associated with wild-type IDH in grade IV glioma." (PMID 30479695, 2018). "High expression of neuropilin-1 is indeed associated with a bad prognosis in glioma patients." (PMID 27506939, 2016). "We thus investigated whether glioma-associated microglia and macrophages (GAMs) express Nrp1 using human tumor biopsies." (PMID 26755653, 2016). "The over-expression of NRP1 enhances tumour growth, correlates with invasive growth and is associated with poor prognosis in gastrointestinal tract, prostate, lung and ovarian tumours as well as gliomas, osteosarcomas and melanomas 15,20,21." (PMID 26147006, 2015). "Moreover, glioma survival times in mice with Nrp1-deficient GAMs were significantly longer." (PMID 26755653, 2016).
glioma (continued). "Genetic or pharmacological inhibition of NRP1 in glioma TAMs reprograms them towards an antitumor phenotype, by reducing angiogenesis and enhancing lymphocyte infiltration, thus delaying tumor progression." (PMID 40805120, 2025). "The administration of EG00229, a selective NRP1 inhibitor, altered gene expression in microglia, enhancing glioma-specific CD8+ T cell immunity and increasing survival in a mouse model of GBs." (PMID 41268299, 2025). "We identify molecular targets that can be used to improve the photosensitizer delivery to glioma cells, such as the epithelial growth factor receptor, neuropilin-1, low-density lipoprotein receptor, and neuropeptide Y receptors." (PMID 39201395, 2024). "Neuropilin-1 has also been successfully used as a target to improve the PS delivery to glioma cells." (PMID 39201395, 2024). "9G-A7R can specifically bind neuropilin-1 and vascular endothelial growth factor receptor 2 overexpressing in glioma cells, enhancing its proteolytic stability in serum and accessibility of A7R to the brain." (PMID 38318188, 2024). "The release of VEGFA and semaphorin 3A (Sema 3A) by tumor cells, including glioma, further activates NRP1, triggering the activation of VEGFR1 and subsequent recruitment of TAMs in glioma." (PMID 39033204, 2024). "Neuropilin-1 (NRP-1) is a transmembrane protein involved in glioma proliferation, invasion, and migration, as well as tumor angiogenesis." (PMID 39201395, 2024). "In glioma stem-like cells, semaphorin 3A binds to Neuropilin 1-plexin A1 (NRP-1-plxA1) complex and activates Src, facilitating the relocation of VE-cadherin." (PMID 39035739, 2024). "To evaluate the potential correlation between the expression levels of the Sema3A/NRP1 axis components with tumor grade and survival, we interrogated TCGA clinical glioma data sets." (PMID 37788099, 2023). "The expression levels of Sema3A and NRP1 strongly correlated with tumor grades, and they were significantly higher in GBMs compared with low-grade gliomas (LGGs)." (PMID 37788099, 2023). "Neuropilin-1 (NRP-1) is selectively expressed in glioma cells and the tumor endothelium and serves as an ideal target of glioma." (PMID 36593970, 2023). "Nrp-1 has been described to be involved in the migration of several cell types including gastric cancer cells, glioma cells and human endothelial cells towards its ligand VEGF." (PMID 38019895, 2023). "In the current study, we further explored the molecular binding mechanisms of TAT-AT7 to VEGFR-2 and NRP-1 and its anti-glioma effects." (PMID 37240099, 2023). "RNAi-mediated knockdown of NRP1 reduces the proliferation of C6 glioma cells stimulated by the NRP1 ligand glia cell line-derived neurotrophic factor (GDNF)." (PMID 37894289, 2023). "Surprisingly, this miRNA has been verified to be a negative regulator of Neuropilin-1 (NRP-1), which is a multifunctional receptor involved in glioma cell proliferation, invasion, and migration through binding to various extracellular receptors." (PMID 35922753, 2022). "In another study, EVs were modified in order to target neuropilin-1 (NRP-1), which is a transmembrane glycoprotein overexpressed in glioma cells and the tumor vascular endothelium." (PMID 36354586, 2022). "Specifically through Kaplan-Meier survival analysis, differences between NRP1 low and NRP1 high populations were observed both in low grade and in high grade gliomas." (PMID 36203599, 2022). "The RGE peptide (RGERPPR) is a tumor-penetrating peptide that possesses a high binding affinity for NRP-1, a transmembrane glycoprotein that is overexpressed on glioma cells." (PMID 35386310, 2022). "The RGERPPR motif shows a high binding affinity for NRP-1, a transmembrane glycoprotein overexpressed on glioma cells." (PMID 35386310, 2022). "The effects of NRP1 on the neurovascular unit are critical in the context of gliomas and glioblastomas." (PMID 36203599, 2022).
glioma (continued). "When both low and high grade glioma patients were combined to represent glioma of all grades, NRP1 Low median survival was 114 months, whereas the NRP1 High median survival was 15.93 months." (PMID 36203599, 2022). "Mounting the previous evidence, cationic liposomes functionalized with two receptor-specific peptides, including Angiopep-2 and neuropilin-1 has been developed for glioma targeting and BBB penetration, respectively." (PMID 35757736, 2022). "The interplay between VEGF, VEGFR2 and Nrp1 in the maintenance of glioma CSC and tumor progression was assessed." (PMID 36203599, 2022). "Our data, therefore, propose a reliable approach to explore invasive properties of patient glioma cells ex vivo and identify NRP1 as a mediator in this malignant process." (PMID 36204684, 2022). "The NRP1 inhibitor EG00229 has also been demonstrated to exert significant tumor-suppressive effects in gliomas and squamous cell carcinomas." (PMID 36970722, 2022). "A previous study demonstrates the importance of VEGF/VEGFR2/NRP1 signaling in the viability, self-renewal, and tumorigenicity of glioma CSCs." (PMID 35773697, 2022). "In this review, we have discussed the involvement of NRP1 in pediatric brain tumors, such as gliomas, MBs, or EPNs." (PMID 34277411, 2021). "This potentiation of HGF activity by NRP1 contributes to the development of certain cancers, such as gliomas and pancreatic ductal adenocarcinomas." (PMID 34277411, 2021). "A tumor-derived protease cleavage exposes the CendR motif that is able to recognize neuropilin-1 (NRP-1) overexpressed on the surface of glioma cells." (PMID 34279392, 2021). "They then conjugated the exosome membrane with neuropilin-1-targeted peptide by click chemistry to get glioma-targeting exosomes with imaging and therapeutic functions." (PMID 34722277, 2021). "NRP1-mediated tumor invasion and growth has been described in several publications studying gliomas and glioblastomas." (PMID 34277411, 2021). "Another study describes the role of NRP1 on LTreg in glioma and shows that a small molecule antagonist of NRP1 is able to block a glioma-conditioned medium-induced increase in TGF-β production in LTreg." (PMID 34277411, 2021). "NRP1 is also expressed in a variety of tumors including leukemia, prostate cancer, breast cancer, pancreatic cancer, and glioma." (PMID 34843522, 2021). "The transmembrane domain of NRP-1 has been a useful target when treating gliomas, exhibiting anti-VEGF effects and offering therapeutic benefit for pathologies aiming to block angiogenesis and tumor progression." (PMID 33395426, 2021). "NRP‐1 is expressed as a multifunctional receptor in various human tumours, including gliomas, and the degree of expression is related to the clinicopathological characteristics of the host tumours." (PMID 33300633, 2021). "NRP1 has been shown to be related to poor prognosis in gliomas and signals through microglia/macrophages." (PMID 34417465, 2021). "Previous work suggested that semaphorin 3C, plexin A2, plexin D1, and Nrp1 form a complex in glioma stem cells, whereas numerous studies have indicated the interaction of semaphorin 3A, plexins, and Nrp1." (PMID 34270956, 2021). "This correlation seems especially high for high grade gliomas, and so reinforces the possible role of NRP1 in tumor progression." (PMID 34277411, 2021). "Although the median survival for Low grade glioma patients with low expression of Sema3A/Nrp1/PlxnA1 is significantly greater than those with high expression, the curves do converge at long-term endpoints." (PMID 33302912, 2020). "While previous studies have shown that Nrp1 is expressed in high and low grade glioma biopsies, our study is the first to show that higher expression of Nrp1, PlxnA1 and Sema3A are all associated with decreased survival in both GBM and LGG cohorts." (PMID 33302912, 2020). "The implication of VEGF/NRP1 pathway was also highlighted in glioma stem cells and in medulloblastoma stem cells." (PMID 32766254, 2020).
glioma (continued). "Aimed at targeting specifically glioma cells, liposomes functionalized with R6dGR peptide (R6dGR-Lip), that is able to recognize integrin receptors ανβ3 and neuropilin-1 (NRP1), a membrane-bound co-receptor of tyrosine kinase receptor, were developed." (PMID 32547395, 2020). "A new NRP‐1 targeting probe has been be used for the grading diagnosis by MRI of gliomas in nude mice." (PMID 32951327, 2020). "Given the differences in survival observed across the two cohorts, and within combined glioma, we next investigated the connection between NRP1 expression and glioma grade." (PMID 30479695, 2018). "Overexpression of Nrp1 by cancerous cells in glioma biopsies has been directly correlated with poorer clinical outcome and worse progression free survival (PFS)." (PMID 32914058, 2018). "Mouse genetics and other studies have found that Plexins A1, A2, and D1 in association with Nrp1 and Nrp2 are receptors for SEMA3C in endothelial cell and glioma stem cells." (PMID 29348142, 2018). "As Nrp1 is widely expressed in gliomas, the use of PET tracers that bind Nrp1 has been investigated in murine models." (PMID 32914058, 2018). "The efficacy and tolerability of other Nrp1-targeting drugs should be considered, and since Nrp1 plays so many roles in the glioma microenvironment, pursuing research in the development and implementation of Nrp1 antagonists in glioma therapy seems fruitful." (PMID 32914058, 2018). "Glioma stem cells have also been shown to secrete VEGF-A, which not only serves to promote angiogenesis, but also enhances the proliferative index of glioma cells in an autocrine fashion via VEGFR2 in complex to Nrp1." (PMID 32914058, 2018). "Based on our animal data, we sought to make meaningful extrapolations about NRP1 expression in human glioma." (PMID 30479695, 2018). "It has been demonstrated that overexpression of NRP-1 in cancer cells promotes tumor angiogenesis and stimulates cancer stem cell feature that depends on the complex NRP-1/VEGFR-2 for the CD133(+) human glioma stem-like cells (GSCs)." (PMID 29632646, 2018). "Sema3A is secreted by glioma-derived cells in vesicles, which have been shown to directly increase vascular permeability by interacting with Nrp1 on endothelial cells in xenograft mouse models." (PMID 32914058, 2018). "Multivariate analysis was carried out in the NRP1 low and high populations across the combined glioma data set." (PMID 30479695, 2018). "We have also shown qualitatively that NRP1 co-localizes with the pan-monocyte marker Iba1 across all glioma grades in archived human biopsies." (PMID 30479695, 2018). "Our present comprehensive analysis of NRP1 expression in human GB, in combination with the conclusions from our murine glioma model, suggest that NRP1 is a valid target to pursue in future work." (PMID 30479695, 2018). "The differentially expressed proteins were annotated using Gene Ontology, and neuropilin-1 (NRP1) was identified as the putative GDNF receptor in glioma." (PMID 29088765, 2017). "In conclusion, we demonstrated that NRP1 was the binding receptor of GDNF in glioma cells with therapeutic potential." (PMID 29088765, 2017). "Immunofluorescence staining demonstrated higher NRP1 expression on the membrane of C6 glioma cells than normal rat astrocytes." (PMID 29088765, 2017). "NRP-1 is a cell surface glycoprotein that is highly expressed in many cancers, including glioma and medulloblastoma." (PMID 28463983, 2017). "Immunofluorescence staining also demonstrated high NRP1 expression in C6 glioma cells compared to normal astrocytes (p<0.05)." (PMID 29088765, 2017). "Treatment of C6 glioma cells with exogenous GDNF resulted in increased expression of NRP1 protein and mRNA." (PMID 29088765, 2017). "In glioma, increased NRP1 expression is observed in endothelial cells and the neoplastic astrocytes of GBM." (PMID 29088765, 2017).